RNU6-913P (RNA, U6 small nuclear 913, pseudogene)
Gene: Small nuclear RNA gene on chromosome 5 (61,664,145 to 61,664,239, reverse strand). Ensembl gene ENSG00000212215.
Homologues: Orthologues: chimpanzee U6 (100% identical), macaque U6 (95% identical), guinea pig RNU6-913P (79% identical), pig U6 (79% identical), rabbit U6 (79% identical), dog U6 (77% identical). Paralogues in human: RNU6-1145P (86% identical), RNU6-16P (86% identical), RNU6-38P (86% identical), RNU6-658P (86% identical), RNU6-1040P (85% identical), RNU6-140P (85% identical), RNU6-20P (85% identical), RNU6-29P (85% identical), RNU6-333P (85% identical), RNU6-73P (85% identical), RNU6-1122P (84% identical), RNU6-1316P (84% identical), and 1284 more.